GDF15 (growth differentiation factor 15)
Diseases named in the same sentence as GDF15 in open-access papers (continued):
Sharing a sentence is not in itself a finding about the gene and the disease.
cancer (continued). "In addition, GDF15 and the ErbB2 receptor are implicated in cancer proliferation." (PMID 34445593, 2021). "However, risk factors for cancer, such as smoking and age, also elevate GDF15 and may also contribute to the raised levels observed in patients with malignancy." (PMID 32310257, 2020). "Therefore, we hypothesize that GDF-15 could be implicated in the development of low muscle mass and body weight loss in cancer patients." (PMID 33396237, 2020). "Although hsa-miR-873-5p and GDF15 levels appeared to be negatively correlated in our in vitro assays, elevated hsa-miR-873-5p or GDF15 levels have been previously associated with different stages of cancer-like cell proliferation, metastasis, and chemoresistance." (PMID 28806401, 2017). "Thus, not only cancer cells themselves but also cancer-associated activated macrophages may contribute serum GDF15 elevation." (PMID 26892343, 2016). "The present study evaluated the hypothesis that GDF-15 is an independent marker of the long-term risk for both cardiovascular disease and cancer morbidity beyond clinical and biochemical risk factors in elderly men, with and without previous manifestations of these diseases." (PMID 24312445, 2013). "Together, this work establishes a versatile artificial intelligence-driven binder design pipeline with broad potential for next-generation diagnostics and therapeutics in cancer cachexia and other GDF15-mediated diseases." (PMID 42104019, 2026). "Growth differentiation factor‐15 (GDF‐15) increases under conditions of cell stress and is elevated in various chronic diseases, including cancer and heart disease." (PMID 41555670, 2026). "For example, cancer cells and placental cytotrophoblasts secrete pro-GDF-15 dimers which remain anchored to the ECM until the pro-domain is cleaved by the matrix metalloproteinase 26 (MMP26) and PCSKs, respectively." (PMID 41590509, 2026). "Elevated circulating GDF15 levels are often observed in pathological states such as cancer, cardiovascular disease, and metabolic disorders, where it acts as an anorexigenic signal via its receptor GFRAL in the hindbrain to suppress appetite." (PMID 41596279, 2026). "These previous studies suggest that GDF15 is potentially useful as a clinical cachectic biomarker for patients with cancer, particularly those facing highly invasive surgery." (PMID 41016991, 2026). "A novel inflammatory marker, growth differentiation factor 15 (GDF15), was recently reported to be associated with cancer cachexia." (PMID 41016991, 2026). "Together, these findings demonstrate the pivotal role of TGFBI in BLCA's stemness maintenance and BLCA progression, highlighting that the inhibition of the TGFBI/GDF15 axis is a potential therapeutic strategy for the amelioration of cancer chemotherapy." (PMID 41684953, 2026). "In the context of cancer, GDF15 has been shown to promote tumor cell proliferation, enhance resistance to apoptosis, and contribute to an immunosuppressive tumor microenvironment, thereby facilitating tumor progression." (PMID 40677718, 2025). "While there are numerous reports describing GDF15-dependent effects in cancer cells, the depth of these effects is complex, diverse, and inconsistent, lacking any clear consensus." (PMID 40128491, 2025). "This review highlights the pathophysiological roles of GDF-15 in cancer, with early-phase clinical trials suggesting its involvement in cancer cachexia and ICI resistance." (PMID 41294666, 2025). "Further investigation is needed to fully elucidate the role of GDF15 in cancer therapy and to develop effective strategies for its modulation." (PMID 40837873, 2025). "To clarify the function of pro-NAG-1/GDF15 in cancer cells, we introduced a NAG-1/GDF15 R193A mutant construct that cannot be cleaved into mature NAG-1/GDF15 and GDPP." (PMID 40316530, 2025). "Ponsegromab, a monoclonal antibody targeting GDF-15, showed promising results in early trials, improving body weight and activity levels in cancer patients." (PMID 40519290, 2025).
cancer (continued). "Nevertheless, excessive GDF-15 expression in chronic diseases, including advanced cancer, heart failure, and kidney failure, induces deleterious effects, ultimately resulting in refractory conditions." (PMID 41294666, 2025). "Owing to the biological importance of GDF15 in various cancers, we developed a GDF15 signaling pathway map using literature mining to gather the molecular interactions in various cancers." (PMID 40128491, 2025). "In vivo, NAG-1/GDF15 expression significantly reduces tumor growth in cancer xenograft models, accompanied by decreased proliferation and increased apoptosis." (PMID 40316530, 2025). "Although inflammatory cytokines, including tumour necrosis factor-alpha (TNF-α), interleukin-1 (IL-1), and IL-6, also play a role in cancer cachexia, their mechanisms differ from those of GDF-15." (PMID 41294666, 2025). "GDF15 is also an important player in cancer cachexia, suggesting a potential role of GDF15 blockade in the management of such a condition." (PMID 41034527, 2025). "Further investigations are necessary to optimize these therapies and clarify the full spectrum of the involvement of GDF15 in cachexia and other cancer-related complications." (PMID 40837873, 2025). "In this study, we investigated the growth differentiation factor 15 (GDF15), a protein with roles in various cancers, to determine its significance in LSCC." (PMID 40725563, 2025). "Current GDF15 research has primarily addressed its functions in cancer and inflammatory diseases, where it modulates immune responses and cell survival." (PMID 41023695, 2025). "First, in cancers such as colorectal cancer and malignant glioma, GDF15 directly reduces the cytotoxicity of NK cells, helping cancer cells evade immune surveillance." (PMID 41516233, 2025). "Monoclonal antibody therapies targeting GDF15 are currently being explored in clinical trials, offering new hope for the treatment of cancer cachexia." (PMID 40837873, 2025). "Among the cancers arising from the head and neck area, there is some data about the role of GDF15 exclusively in a specific subsite, such as the oral cavity." (PMID 40868185, 2025). "Overall, while targeting GDF15 represents a promising investigational approach in cancer cachexia and potentially in combination with immunotherapy or chemotherapy, the available evidence remains preliminary." (PMID 40868185, 2025). "According to data from literature, GDF15 and IL-6 are likely produced at the tumor site, composed of cancer cells as well as various infiltrated cell populations in the tumor microenvironment." (PMID 40124481, 2025). "In several adult disease states, including cancer cachexia and pregnancy, circulation and expression of GDF15 has been of clinical and scientific interest, but little published paediatric data exists." (PMID 40019842, 2025). "GDF15 also plays a role in iron metabolism dysregulation, cancer stem cell maintenance, and tumor spheroid formation." (PMID 40868185, 2025). "GDF-15 has been strongly associated with aging and age-related pathologies, including CVD, cancer, and frailty, showing consistently elevated levels in older adults." (PMID 41281356, 2025). "GDF-15 plays a key role in anorexia and muscle wasting in patients with cancer, where various cytokines and humoral factors also contribute to these effects, acting through non-neural pathways and directly impacting peripheral organs." (PMID 41294666, 2025). "Based on the preclinical findings of the role of GDF-15 in cancer cachexia and tumour immunity, early-phase clinical trials have explored GDF-15 inhibition to manage cancer cachexia and enhance immunotherapy efficacy, demonstrating promising results." (PMID 41294666, 2025).
cancer (continued). "GDF15 has been implicated in shaping immunosuppressive tumor microenvironments (TME) and promoting radioresistance in various cancers 36, 51-53, but its role in GBM remained unclear." (PMID 41281763, 2025). "GDF15 was shown to play a pivotal role in resveratrol-induced growth inhibition of various types of cancer cell lines." (PMID 40837873, 2025). "Among the key molecular mediators of cancer cachexia are inflammatory proteins such as Growth Differentiation Factor-15 (GDF-15) and interleukin-6 (IL-6)." (PMID 40807373, 2025). "Importantly, the study also highlights that the loss of GDF15 under diabetic conditions contributes to a permissive environment for tumor expansion by enhancing stromal cell migration, which may further facilitate cancer dissemination." (PMID 41009692, 2025). "Considering the biological importance of GDF15 in different cancers, we applied data mining techniques to systematically compile and analyze the signaling events associated with GDF15 using NetPath criteria." (PMID 40128491, 2025). "The positive association between cancer and IL-10 was mediated 5.6% by TNFR1 and 4.1% by IL-6 independently, while the positive association for GDF15 was mediated 36.1% by TNFR1 and 10.5% by IL-6 independently." (PMID 41280118, 2025). "The trends approaching statistical significance in DFS and overall survival observed in the TCGA and GEO datasets suggest the potential broader significance of GDF15 expression in cancer prognosis." (PMID 40725563, 2025). "Two studies showed elevated GDF15 levels in paediatric patients with cancer who had received anthracycline chemotherapy treatment months to years earlier." (PMID 40019842, 2025). "Although initially characterized for its anti-inflammatory effects on macrophages, GDF-15 is now recognized as a pleiotropic molecule involved in diverse pathological states, including cardiovascular diseases, kidney disease, cancer, and metabolic disorders." (PMID 41157213, 2025). "The rationale for selecting GDF15 stems from its emerging role in tumor progression, immune modulation, and cancer-related systemic effects such as cachexia." (PMID 40725563, 2025). "Recently, early clinical trials have reported preliminary results of GDF-15-targeted therapies in alleviating cancer cachexia and potentially enhancing the efficacy of immunotherapy." (PMID 41294666, 2025). "GDF-15 is overproduced in the placenta during pregnancy and in diseases, including cancer, cardiovascular diseases, and metabolic disorders." (PMID 41294666, 2025). "Preclinical studies have shown that antibodies against GDF15 and GFRAL effectively counteract weight loss in tumor-bearing mice, suggesting their potential as therapeutic targets for cancer cachexia." (PMID 40519290, 2025). "GDF-15 values are raised in pathological disorders such as cancer, liver diseases, kidney diseases, metabolic diseases, and cardiovascular disorders." (PMID 39781722, 2025). "Preclinical studies highlight the critical role of the GDF-15/GFRAL pathway in cancer cachexia, with its inhibition mitigating symptoms." (PMID 41294666, 2025). "measured GDF15 levels at diagnosis (prior to treatment) and reported elevated GDF15 levels in paediatric patients with cancer, which persisted through three months of treatment." (PMID 40019842, 2025). "Growth differentiation factor 15 (GDF-15) is a critical mediator of cancer cachexia, making it an attractive therapeutic target." (PMID 41294666, 2025). "Fifth, the amplitude of the observed fluctuations was small compared with the fluctuations of other metabolic markers and compared to the levels of GDF15 observed, for example, in pregnancy and cancer." (PMID 41277741, 2025). "In this prospective cohort study of 779 cancer patients, we evaluated the prognostic potential of GDF-15 as a biomarker for major bleeding (Central Illustration)." (PMID 39967200, 2025).
cancer (continued). "While the pathogenesis of cancer cachexia involves metabolic, immune, and endocrine disruptions, GDF15 has emerged as one of the central players in this pathology." (PMID 40837873, 2025). "Growth differentiation factor 15 (GDF15), elevated in several cancer types, signals through its receptor GFRAL in the area postrema and nucleus of the solitary tract (NTS), regions involved in nausea and appetite regulation." (PMID 40704145, 2025). "Growth differentiation factor 15 (GDF15), a member of the transforming growth factor-β (TGF-β) superfamily, has been implicated in various pathological conditions, including cancer and inflammation." (PMID 41023695, 2025). "As neoadjuvant or adjuvant immunotherapy becomes standard, the dual benefits of GDF-15 inhibition, including mitigating cancer cachexia and enhancing ICI immunocompetency, make this approach an attractive strategy alongside chemotherapy and/or immunotherapy." (PMID 41294666, 2025). "Previous studies have shown that GDF15 neutralization is effective in improving skeletal muscle mass and function in cancer cachexia." (PMID 39976232, 2025). "In radiotherapy, GDF15 is markedly induced by radiation in several cancers, suggesting its role in acquired radioresistance 33-39." (PMID 41281763, 2025). "This research contributes to a better understanding of GDF15’s role in cancer and highlights its potential utility in improving LSCC management." (PMID 40725563, 2025). "GDF-15 primarily regulates appetite and cell metabolism, and its targeted treatment can directly mediate cancer cachexia." (PMID 41294666, 2025). "As a key marker of oxidative stress, GDF15 possesses independent prognostic value in cancer and cardiovascular and aging-related diseases." (PMID 41035818, 2025). "This resulted in constructing a detailed GDF15-mediated signaling pathway map, enhancing our understanding of its molecular mechanisms in cancer." (PMID 40128491, 2025). "More recently, inhibition of growth differentiation factor 15 (GDF-15) has been proposed as a potential therapeutic approach with encouraging results in patients with cancer cachexia." (PMID 39874717, 2025). "Elevated levels of GDF15 occur in various cancers, including prostate, colon, and pancreatic cancers, and is closely related to weight loss and a decrease in body mass index (BMI)." (PMID 40837873, 2025). "In preclinical cancer models, blocking GDF-15 synergistically improved the effectiveness of anti-PD-1." (PMID 40732268, 2025). "This study underscores the power of computational approaches, such as data mining and molecular docking, in enhancing our understanding of GDF15 signaling in cancer and identifying potential inhibitors for therapeutic development." (PMID 40128491, 2025). "Differential analysis between high-risk and low-risk cancer cells revealed that high-risk cancer cells exhibited elevated expression of genes associated with M2 macrophages, including CXCL2, IL6R, CXCL8, GDF15, CD68, and PTX3." (PMID 41034991, 2025). "The emerging role of GDF15 in oncology represents a paradigm shift in the management of both cancer progression and CC." (PMID 40868185, 2025). "Ponsegromab, a monoclonal antibody that neutralises GDF-15, is an actively studied agent for cancer cachexia." (PMID 41294666, 2025). "These dual effects of metabolic dysregulation and immune escape make GDF-15 a highly attractive therapeutic target for reversing cancer cachexia, enhancing immunity, and improving systemic immunotherapy efficacy." (PMID 41294666, 2025). "Analyses of the predictive ability of GDF-15 revealed good performance in both discrimination and calibration for predicting 6-month major bleeding in this cancer cohort." (PMID 39967200, 2025). "Although the serum level of GDF15 in health subjects is <0.5 ng/ml, serum GDF15 level can increase to ~30–100 ng/ml after therapeutic GDF15 injection or >5 ng/ml in patients with cancer cachexia." (PMID 41034527, 2025).
cancer (continued). "Specifically murine models in the context of cancer are also in focus of current research for both IL‐6 and GDF‐15." (PMID 41380167, 2025). "Although other studies have investigated the effects of GDF15-neutralizing antibodies in the treatment of cancers, this was the first study to explore the antitumor activity of AZD8853 monotherapy." (PMID 40354065, 2025). "This suggests GDF15 as a potential therapeutic target for mitigating chemotherapy-induced toxicity, enhancing the quality of life for cancer patients undergoing treatment." (PMID 40837873, 2025). "In other settings, GDF15 contributes to cancer cachexia, and it is conceivable that both secreted factors are operative in some settings." (PMID 40964365, 2025). "A subsequent phase 1b study evaluated the safety and preliminary efficacy of ponsegromab in patients with advanced solid tumours who met Fearon’s criteria for cancer cachexia and exhibited elevated serum GDF-15 concentrations (≥1500 pg/mL)." (PMID 41294666, 2025). "Conversely, an RCT targeting GDF15 inhibition for cancer cachexia treatment observed weight gain after 12 weeks, indicating a role for GDF15 in weight regulation." (PMID 40527012, 2025). "This would be especially useful for opto-PKR, given the relatively high baseline expression of GDF15 observed here, which is consistent with high GDF15 expression in several cancer cell lines (see Human Protein Atlas26)." (PMID 39975214, 2025). "GDF15 also exhibits a notable increase in a variety of pathological conditions, including cancer and cachexia." (PMID 39700016, 2024). "Experiments conducted with different models have revealed that the knockdown of GDF15 significantly inhibited the migration, invasion, and proliferation of cancer cells." (PMID 39643709, 2024). "Earlier studies have identified GDF-15 as a potential target for treating cachexia in patients with advanced cancer." (PMID 38335385, 2024). "Cancer cells stimulate the release of FAs from nearby adipocytes through the secretion of soluble substances, including hormone-sensitive lipase and growth differentiation factor 15 (GDF15)." (PMID 38933330, 2024). "In various pathological states, such as cancer, cardiovascular diseases and chronic kidney disease, upregulation of endogenous GDF15 is considered an adaptive stress response, with potential anti‐inflammatory and protective functions." (PMID 39700016, 2024). "For these reasons, the GDF15 protein was proposed to be an excellent prognostic marker not only for cancers and chronic diseases but also for the biological aging process itself." (PMID 39643709, 2024). "High serum levels of GDF-15 represent a poor prognostic factor for cancer patients as circulating levels of GDF-15 have been shown to positively correlate with weight loss, and negatively correlate with lean body and muscle mass." (PMID 39001427, 2024). "The development and application of monoclonal antibodies targeting GDF15 for targeted cancer cachexia therapy represent a potentially effective approach to enhance cancer survival rates and treatment outcomes." (PMID 39172988, 2024). "Butyrate administration significantly decreased the tumor size and levels of the immunosuppressive markers (PD-L1 and IL-10), their regulators (NF-KB and STAT3), and cancer growth factor (VEGF and GDF-15) in cancer tissues." (PMID 38197259, 2024). "These experiments indicated that the PD-L1 protein induced by GDF15 exposure allowed cancer cells to evade surveillance and immune elimination by cytotoxic T cells." (PMID 39643709, 2024). "The aim of this study is to support the clinical development of ponsegromab as a novel inhibitor of GDF‐15‐mediated signalling and potential therapy for cancer cachexia." (PMID 38500292, 2024). "Our study also supports previous findings connecting elevated GDF-15 levels with cancer cachexia, a condition that severely diminishes patients’ functional status and quality of life." (PMID 39766045, 2024).